DLD (dihydrolipoamide dehydrogenase)
Diseases named in the same sentence as DLD in open-access papers (continued):
Sharing a sentence is not in itself a finding about the gene and the disease.
Obesity (3 papers, 2018 to 2025). Accumulation of substantial excess body fat. "This network included aconitate hydratase 2 (ACO2), and dihydrolipoyl dehydrogenase (DLD), in which acetylation was significantly increased by obesity." (PMID 30061171, 2018).
Sepsis (3 papers, 2021 to 2025). Sepsis is defined as life-threatening organ dysfunction caused by a dysregulated host response to infection. "The top five gene variables (MTF1, UBE2D2, DLAT, DLD, and ULK2) were selected as disease signature genes in the GLM model to construct a nomogram for predicting the incidence of sepsis-associated ALI." (PMID 38779731, 2025). "The expression of SLC31A1, CD274, ATOX1, MTF1, UBE2D1, DLD, and VEGFA was found to be upregulated, while that of DLST, UBE2D2, COX11, DLAT, GLS, FDX1, and ULK2 were significantly downregulated in patients with sepsis-associated ALI." (PMID 38779731, 2025). "Finally, the 6 DECuGs (ANKRD9, DLD, LIPT1, MTF1, PDHB, UBE2D4) as diagnostic biomarkers for sepsis were identified by the intersection of the two machine learning algorithms." (PMID 38495196, 2024). "Next, six key DECuGs (ANKRD9, DLD, LIPT1, MTF1, PDHB, UBE2D4) were identified as diagnostic biomarkers based on the two machine learning algorithms, suggesting their potential functional importance in the pathogenesis of sepsis." (PMID 38495196, 2024). "For immune cells, monocytes, T cells, B cells, and NK cells were related to DLD, LIPT1, MTF1, PDHB and UBE2D4 in the sepsis group." (PMID 38495196, 2024).
Ataxia (2 papers, 2020 to 2025). Ataxia refers to impaired coordination of voluntary muscle movement. "The patient with DLD deficiency revealed moderate developmental delay/psychomotor retardation, seizures, hypotonia, dystonia and ataxia." (PMID 33092611, 2020). "As a result, DLD deficiency typically causes severe neonatal-onset metabolic decompensation, with features such as lethargy, hypotonia, seizures, developmental delay, and ataxia, and frequently leads to early death." (PMID 41018056, 2025).
bladder cancer (2 papers, 2014 to 2024). "We therefore examined the expression of components of the pyruvate dehydrogenase complex (PDC), and found that the third component of the complex, dihydrolipoyl dehydrogenase (DLD), is significantly reduced in bladder cancer (p < 10-7)." (PMID 24721970, 2014).
COVID-19 (2 papers, 2024). A disease caused by infection with severe acute respiratory syndrome coronavirus 2. "Our study found that six CRGs (SLC31A1, SLC31A2, MT4, SNCA, UBE2D4, DLD) play important roles in the pathological mechanism of COVID-19." (PMID 38581529, 2024). "Univariate analysis and machine learning confirm that dihydrolipoamide dehydrogenase (DLD) is the common key gene of COVID-19 and DLBCL." (PMID 38581529, 2024). "The cuprotosis related DLD gene has been proven to be a potential therapeutic target for COVID-19 infected DLBCL patients, suggesting that CRGs play an important role in the mechanism of COVID-19 infected DLBCL patients." (PMID 39008196, 2024). "Research has found that DLD is a differentially expressed gene that is shared by DLBCL and COVID-19, DLD may therefore be a key gene in promoting the development and occurrence of DLBCL by COVID-19." (PMID 38581529, 2024). "DLD may therefore be potential therapeutic target and a key gene for COVID-19 to promote DLBCL’s progression." (PMID 38581529, 2024). "Research has found that DLD is a differentially expressed gene shared by COVID-19 and DLBCL, therefore, DLD may be a key gene in promoting the occurrence and development of DLBCL by COVID-19." (PMID 38581529, 2024). "COVID-19 and DLBCL share a common signal crosstalk mechanism and cuprotosis related DLD gene have been proved to be potential therapeutic targets for DLBCL patients infected with COVID-19." (PMID 39008196, 2024). "Therefore, DLD may be a common pathological gene between COVID-19 and DLBCL." (PMID 38581529, 2024).
diffuse large B-cell lymphoma (2 papers, 2022 to 2024). "However, a large majority of cuproptosis-associated genes including FDX1, LIAS, LIPT1, DLD, DLAT, and PDHB acted as a low-risk indicator in Lymphoid neoplasm diffuse large B-cell lymphoma (DLBC)." (PMID 36105090, 2022).
Encephalopathy (2 papers, 2016 to 2022). Encephalopathy is a term that means brain disease, damage, or malfunction. "A deficiency of DLD may lead to a range of presentations, mostly characterized by severe neurological impairment in early childhood with encephalopathy and seizures." (PMID 27303803, 2016).
endometrial cancer (2 papers, 2016 to 2021). Primary or metastatic malignant neoplasm involving the endometrium (mucous membrane that lines the endometrial cavity). "DLD has been found to be a major autoantigen in hepatitis C virus infection and a target of autoantibodies in endometrial cancer." (PMID 27303803, 2016).
head and neck squamous cell carcinoma (2 papers, 2023). A squamous cell carcinoma that arises from any of the following anatomic sites: lip and oral cavity, nasal cavity, paranasal sinuses, pharynx, larynx, and salivary glands. "In head and neck squamous cell carcinoma, dihydrolipoamide dehydrogenase regulates cell death through cystine deprivation." (PMID 37827692, 2023). "By contrast, the expression of DLD was lower in LIHC, BRCA, head and neck squamous cell carcinoma (HNSC), PAAD, KIRC, COAD and GBM compared with that in normal tissues." (PMID 37123026, 2023).
liver disease (2 papers, 2016 to 2020). "The relative concentrations of serum dihydrolipoyl dehydrogenase (DLD), which showed the most significant correlation with liver diseases and infection, were significantly lower in HCC patients than asymptomatic HBsAg carriers and individuals negative for HBsAg." (PMID 27303803, 2016).
ovarian carcinoma (2 papers, 2022 to 2023). A malignant neoplasm originating from the surface ovarian epithelium. "DLD was found to be highly expressed in colon, liver, lung, stomach, renal, corpus uteri endometrial and ovarian cancers compared with normal tissues, and its high expression was associated with poorer prognosis in ovarian cancer." (PMID 37123026, 2023). "In the present study, DLD expression was found to be high in the ovarian cancer OC3 cell line, compared with the normal ovarian epithelial IOSE80 cell line by reverse transcription-quantitative PCR analysis." (PMID 37123026, 2023). "We explored the potential of YY1, FDX1, DLD, DLAT, and PDHB to serve as non-invasive diagnostic markers of ovarian cancer." (PMID 36484005, 2022). "We used an exosome database for screening and found that the levels of FDX1, DLD, DLAT, PDHB, and YY1 in peripheral blood exosomes from ovarian cancer patients were significantly higher than those in the normal controls." (PMID 36484005, 2022). "The results of the cDNA expression profile analysis showed that four factors (i.e. FDX1, DLD, DLAT, PDHB) were highly expressed in the tumor tissues of ovarian cancer patients." (PMID 36484005, 2022). "Bioinformatics analysis revealed that four core factors (lipoic acid pathway FDX1, DLD, DLAT, PDH), and transcription factor YY1 were highly expressed in ovarian cancer tissues and were significantly correlated with an unfavorable prognosis." (PMID 36484005, 2022). "Our study revealed that the expression of four core factors of the lipoic acid pathway (i.e., FDX1, DLD, DLAT, and PDHB) was distinct between ovarian cancer patients and normal tissues and that it was significantly correlated with a poor prognosis inovarian cancer patients." (PMID 36484005, 2022). "In addition, the expression levels of YY1 in the tissue samples from ovarian cancer patients were significantly positively correlated with the expression levels of FDX1, DLD, DLAT, PDHB, and other genes." (PMID 36484005, 2022).
acute liver failure (1 paper, 2024). Rapid deterioration of liver function causing encephalopathy and coagulopathy. "Dihydrolipoamide dehydrogenase (DLD) deficiency can, in one of its forms, be a rare cause of acute liver failure." (PMID 39544687, 2024).
cardiac hypertrophy (1 paper, 2022). "In a mouse model of transverse aortic constriction (TAC)-induced cardiac hypertrophy, the 2-hydroxyisobutylation of DLD was significantly increased, related to the decrease in PDH activity." (PMID 36572672, 2022). "In subsequent studies, other methods should be used to knock down P300 to confirm further the role of P300 in ginsenoside Rg3 in regulating the 2-hydroxyisobutylation level of DLD protein and reducing TAC-induced cardiac hypertrophy in mice." (PMID 36572672, 2022).
Cerebral ischemia (1 paper, 2024). Restriction of arterial blood supply to the brain associated with insufficient oxygenation to support the metabolic requirements of the tissue. "The present study also identified DLD as one of the hub genes responsible for cuproptosis following cerebral ischemia." (PMID 39360273, 2024). "Eight hub genes (FDX1, LIPT1, LIAS, DLD, PDHA1, DLAT, PDHB, and GLS) were identified as potential core targets of cerebral ischemia." (PMID 39360273, 2024).
cervical cancer (1 paper, 2021). A primary or metastatic malignant neoplasm involving the cervix. "Co-IP assays with an anti-STAT5A antibody demonstrated that endogenous STAT5A interacted with multiple PDC subunits, including PDHA1, PHDB, DLD, and DLAT in 293T, HeLa (a human cervical cancer cell line), MIHA (a human hepatocyte), and primary mouse hepatocytes." (PMID 34148062, 2021).
cholangiocarcinoma (1 paper, 2023). A carcinoma that arises from the intrahepatic biliary tree (intrahepatic cholangiocarcinoma) or from the junction, or adjacent to the junction, of the right and left hepatic ducts (hilar cholangiocarcinoma). "In the TCGA datasets, it was found that in Cholangiocarcinoma (CHOL), liver hepatocellular carcinoma (LIHC), lung squamous cell carcinoma (LUSC), kidney chromophobe (KICH) and stomach adenocarcinoma (STAD), the expression of DLD was higher compared with that in the corresponding control tissues." (PMID 37123026, 2023).
cognitive decline (1 paper, 2023). "Pearson correlation analysis found that the IDH3G, DLD, SUCLA2, MDH1 showed moderate positive correlations with MMSE scores (r = 0.365–0.441, p < 0.05), suggesting that their expression can effectively track the progression of cognitive decline." (PMID 37575300, 2023).
cutaneous leishmaniasis (1 paper, 2025). Leishmaniasis affecting the skin. "Using immunoproteomics approach, we identified that DLD63-79 peptide derived from Leishmania major DLD, an important metabolic enzyme in the parasite, as a strong inducer of CD4+ T cell response in a mouse model of experimental cutaneous leishmaniasis." (PMID 40096189, 2025).
dementia (1 paper, 2020). Loss of intellectual abilities interfering with an individual's social and occupational functions. "Activities of TCA cycle enzymes in brains from patients with autopsy-confirmed AD and clinical dementia ratings (CDRs) before death have been measured, and significant (p <0.01) decreases in the activities of the PDH complex, IDH, and the DLD complex, and increases in SDH and MDH were reported." (PMID 32219020, 2020).
hepatocellular carcinoma (1 paper, 2022). A malignant tumor that arises from hepatocytes. "Transmembrane protein 27 (CLTRN, also known as TMEM27) is a type Ia transmembrane, which can be regulated by the Nrf-1/RAN/DLD protein complex to deplete GSH and enhance the radiosensitivity of hepatocellular carcinoma (HCC) cells." (PMID 36176274, 2022).
hypertrophic cardiomyopathy (1 paper, 2023). A condition in which the myocardium is hypertrophied without an obvious cause. "This includes, on the rarer end of the phenotypic spectrum, hypertrophic cardiomyopathy, which is observed in individuals with biallelic variants in DLD, SDHA, SDHB, and SDHD." (PMID 38031187, 2023).
liver fibrosis (1 paper, 2025). "The analysis revealed significant changes in the expression of several key genes in the model group, with notable differences in the expression of RAB18 and DLD, suggesting that these genes may play important regulatory roles in the onset and progression of liver fibrosis." (PMID 40213908, 2025). "With the downregulation of RAB18 protein, the expression of DLD and P62 proteins also significantly decreased, indicating that RAB18 plays a key role in the regulation of liver fibrosis by modulating lipophagy and cuproptosis." (PMID 40213908, 2025). "At the same time, the expression of P62, DLD, PACS‐2, MFN2, lipoic acid‐modified proteins, and DLAT oligomerized proteins significantly increased, suggesting that DATs exert therapeutic effects on liver fibrosis by inhibiting lipophagy and inducing cuproptosis." (PMID 40213908, 2025).
lung diseases (1 paper, 2017). "The significant Ago2-IP enrichment of targets of these miRNAs related to the TGF-β and/or Wnt pathways (NGF, DLD, HHEX) in TGF-β1-stimulated fibroblasts suggest a role for these miRNAs in lung diseases by affecting lung fibroblast function." (PMID 28910321, 2017).
neuroblastoma (1 paper, 2025). Neuroblastoma (NB) is the most common solid, extracranial childhood tumor. "Pharmacological interventions targeting DLD activity, cytosolic NADH, mPTP opening, purine biosynthesis, or energy stress effectively rescued Cu-induced cell death in SH-SY5Y neuroblastoma cells." (PMID 41346305, 2025).
nonalcoholic fatty liver disease (1 paper, 2023). "Dihydrolipoamide dehydrogenase (DLD), as a cuproptosis-related gene, is associated with steatosis and plays an important role in nonalcoholic fatty liver disease." (PMID 37434203, 2023).
pulmonary fibrosis (1 paper, 2023). Chronic progressive interstitial lung disorder characterized by the replacement of the lung tissue by connective tissue, leading to progressive dyspnea, respiratory failure, or right heart failure. "It’s reported that the CRGs, such as FDX1, LIAS, DLD, PDHA1, PDHB, DLAT, and LIPT1, were down-regulated in the lung tissues of pulmonary fibrosis mouse model, and the same results were obtained via analysis of lung tissues scRNA-seq data for human pulmonary fibrosis." (PMID 37266442, 2023).
pyruvate dehydrogenase deficiency (1 paper, 2021). A rare neurometabolic disorder characterized by a wide range of clinical signs with metabolic and neurological components of varying severity. "These included initiation of a ketogenic diet to patients with pyruvate dehydrogenase deficiency (mutations in PDHA1, PDHB, DLD), AGC1 deficiency (mutations in SLC25A12), and GLUT1 deficiency (mutations in SLC2A1)." (PMID 33726816, 2021).
skin aging (1 paper, 2020). The gradual irreversible changes in structure of skin that occur as a result of the passage of time.. "The DLD protein is a part of several multi-enzyme complexes involved in energy metabolism, and it has also been proposed as a biomarker for UV radiation induced skin aging." (PMID 33382739, 2020).
type 1 diabetes mellitus (1 paper, 2023). A chronic condition characterized by minimal or absent production of insulin by the pancreas. "Our analysis revealed that overexpression of DLD activated glycosaminoglycan degradation, galactose metabolism, hematopoietic cell lineage, intestinal immune network for IgA production, Leishmania infection, type I diabetes mellitus, base excision repair, and other pathways." (PMID 37822923, 2023).
tumor (55 papers, 2019 to 2025). "Surprisingly, IDH2R140Q mutation changed the expression patterns of cupropotosis-associated genes, including FDX1, LIAS, LIPT1, DLD, DLAT, and PDHA1, which indicated that the sensitivity of tumor cells to cuproptosis depends on the types of genetic mutations." (PMID 40384935, 2025). "Next, we established a human MM cell line xenograft mouse model in immunodeficient mice, after tumor-bearing in mice, we confirmed the knockdown of DLD in mice by IHC analysis." (PMID 39138149, 2024). "The expression level of DLD was downregulated in 8 tumor types including BLCA, BRCA, COAD, KIRC, PCPG, PRAD, READ, and THCA." (PMID 37113760, 2023). "The heatmap showed that these genes were upregulated in tumor tissue The interaction network involving these genes indicated that DLD, DLAT, and PDHB were the hub genes." (PMID 36386799, 2022). "Meanwhile, a large majority of cuproptosis-associated genes including FDX1, LIAS, DLD, DLAT, PDHA1, and GLS, were significantly associated with the tumor microenvironment (immune, stromal, and estimate scores) (p < 0.05)." (PMID 36105090, 2022). "Cd down-regulates the expression of Star, Cyp11a1, and Hsd3b1 by inhibiting cAMP/PKA/ERK1/2 and PKC signaling after inhibiting of dihydrolipoamide dehydrogenase activity in R2C tumor LCs." (PMID 32528534, 2020). "Cd concentration-dependently lowers cAMP and down-regulates the expression of dihydrolipoamide dehydrogenase in R2C tumor LCs." (PMID 32528534, 2020). "DLD is a key gene involved in “cuproptosis,” but its roles in tumor progression and immunity remain unclear." (PMID 37113760, 2023). "Tumor cells depend on glutaminolysis fuelling to carry out the TCA cycle and essential biosynthetic processes supporting tumor growth, and DLD, a dehydrogenase found in several multi-enzyme complexes that regulate energy metabolism, plays an important role in the tumor biological process." (PMID 37123026, 2023). "In conclusion, the DLD gene may promote the production of ROS to form a state of oxidative stress in the tumor and then stimulate tumor cells to obtain metabolic plasticity to enhance their invasion ability." (PMID 36591111, 2022). "Notably, the high-risk group presented overexpression of three cuproptosis biomarkers: CDKN2A, DLD, and DLAT; moreover, tumor tissues of this group have more tumor mutation burden and less immune cell infiltration." (PMID 36003780, 2022). "Hence, FDX1, DLD, DLAT, and CDKN2A may play important roles in immune interactions and may be associated with tumor immune evasion." (PMID 36531222, 2022). "In the GPL570 dataset, upregulation of LIPT1, FDX1, LIAS, DLAT, DLD, and PDHB was noted in tumor samples, while MTF1 was downregulated." (PMID 40410601, 2025). "Difference analyses showed that 7 of 10 CRGs were dys-regulated in tumor samples compared with those in normal samples, among which LIPT1, PDHA1, GLS and CDKN2A were up-regulated, and FDX1, DLD and MTF1 were down-regulated." (PMID 37333810, 2023). "Among these tumor types, BLCA, COAD, LIHC, LUSC, PAAD, READ, and TGCT showed significantly decreased DLD promoter methylation, while BRCA showed a significant increase." (PMID 37113760, 2023). "In tumor tissues, the abundance of CDKN2A and MTF1 were higher, as well as the levels of DLD, FDX1, GLS, LIPT1 and PDHB were down-regulated." (PMID 37662947, 2023). "The PDAC patients with higher expression levels of PDHA1, LIPT1, LIAS, and DLD, or lower expression levels of DLAT, in their tumor tissues had a better prognosis than their counterparts (p < 0.05)." (PMID 36826087, 2023). "Gene expression profiling showed that SLC31A1, LIPT2, CDKN2A, and GCSH expression was increased in tumor tissues, while NFE2L2, NLRP3, ATP7A, DLD, MTF1, and DLST expression was decreased in tumor tissues compared with normal tissues." (PMID 37065485, 2023).